SSPN (sarcospan)
Description:
Component of the dystrophin-glycoprotein complex (DGC), a complex that spans the muscle plasma membrane and forms a link between the F-actin cytoskeleton and the extracellular matrix. Preferentially associates with the sarcoglycan subcomplex of the DGC.
Synonyms: KRAG; SPN1; SPN2; DAGA5; NSPN
Tractability: Antibody: its Gene Ontology location is reachable by antibodies, with high confidence; UniProt places it where antibodies can reach, with medium confidence; UniProt predicts a signal peptide or a membrane-spanning region.
Gene: Protein-coding gene on chromosome 12 (26,121,991 to 26,299,290, forward strand). Ensembl gene ENSG00000123096.
Subcellular location: Cell membrane; Cell membrane, sarcolemma; Postsynaptic cell membrane
Subcellular location (Human Protein Atlas): Nuclear membrane; Nucleoplasm
Pathways (Reactome):
Extracellular matrix organization: Formation of the dystrophin-glycoprotein complex (DGC)
Gene Ontology:
Biological process: camera-type eye development; cell adhesion; muscle contraction
Cellular component: transport vesicle; dystrophin-associated glycoprotein complex; Golgi membrane; neuromuscular junction; plasma membrane; sarcolemma; membrane; postsynaptic membrane
Genetic constraint (gnomAD): Loss-of-function variants: 14 observed, 13.9 expected, observed/expected ratio (o/e) 1.01, 90% interval 0.66 to 1.57. The upper end of that interval is the gene's LOEUF score, 1.57, which puts it in group 6 of 6, group 1 being the genes least tolerant of losing a copy. Missense variants: 285 observed, 268.18 expected, observed/expected ratio (o/e) 1.06, 90% interval 0.96 to 1.17. Synonymous variants: 146 observed, 120.98 expected, observed/expected ratio (o/e) 1.21, 90% interval 1.05 to 1.38.
Homologues: Orthologues: chimpanzee SSPN (99% identical), macaque SSPN (99% identical), guinea pig SSPN (91% identical), pig SSPN (88% identical), dog SSPN (88% identical), rabbit SSPN (83% identical), mouse Sspn (75% identical), rat Sspn (75% identical), tropical clawed frog SSPN (56% identical), zebrafish sspn (42% identical), Drosophila melanogaster CG1806 (20% identical).
Diseases named in the same sentence as SSPN in open-access papers:
SSPN is named in the same sentence as 23 diseases in open-access papers, as found by Europe PMC text mining. Sharing a sentence is not in itself a finding about the gene and the disease. The quoted sentences say what the papers report.
muscular dystrophy (6 papers, 2017 to 2025). Muscular dystrophy (MD) refers to a group of more than 30 genetic diseases characterized by progressive weakness and degeneration of the skeletal muscles that control movement. "Using transgenic overexpression of SSPN, we show a robust amelioration of γ-sarcoglycan–deficient muscular dystrophy through corrected histopathology and muscle function." (PMID 40549548, 2025). "In mice, Sarcospan (SSPN) plays important roles in muscular dystrophy and muscle force development by linked to sarcoglycans or as a component of the dystrophin-glycoprotein complex." (PMID 29141033, 2017). "Prior evidence in the mdx model and those in Sgcg mice shown here implicate SSPN as a promising target in at least 2 forms of muscular dystrophy." (PMID 40549548, 2025). "An example novel gene is SSPN, encoding sarcospan, a core component of the tetrameric dystrophin-glycoprotein complex (DGC) typically associated with muscular dystrophies." (PMID 38771459, 2024). "Our antibodies recognize human and mouse SSPN and create a unique tool for detecting this protein in patients with muscular dystrophies and the murine models of muscle diseases." (PMID 38892308, 2024). "Overexpression of sarcospan in mdx mice (mdxTG) ameliorates muscular dystrophy by increasing expression of integrins at the sarcolemma, which restores muscle fiber attachment to laminin in the basement membrane and protects the muscle from contraction-induced injury." (PMID 36922514, 2023). "Development of small molecule therapies that increase SSPN expression may lead to stand-alone or combinatorial therapies to treat DMD and other forms of muscular dystrophy caused by deficits in membrane proteins." (PMID 31831063, 2019).
Duchenne muscular dystrophy (3 papers, 2013 to 2024). Duchenne muscular dystrophy (DMD) is a neuromuscular disease characterized by rapidly progressive muscle weakness and wasting due to degeneration of skeletal, smooth and cardiac muscle. "SSPN overexpression ameliorates Duchenne muscular dystrophy in the mdx murine model, which supports SSPN being a viable therapeutic target." (PMID 38892308, 2024). "Overexpression of SSPN ameliorates Duchenne muscular dystrophy in murine models." (PMID 28587652, 2017). "We have previously shown that SSPN is absent in muscle biopsies from Duchenne muscular dystrophy (DMD) patients and is lost in LGMD patients with complete or partial absence of the sarcoglycan complex." (PMID 38892308, 2024).
atrial fibrillation (2 papers, 2023). A disorder characterized by an electrocardiographic finding of a supraventricular arrhythmia characterized by the replacement of consistent P waves by rapid oscillations or fibrillatory waves that vary in size, shape and timing and are accompanied by an irregular ventricular response. "The loci we associated with coronary artery disease (FOXC1), myocardial infarction (USP39), and atrial fibrillation (SLC35F1 and SSPN) through their effects on RHR have been associated with these cardiovascular diseases in recent studies." (PMID 37532724, 2023). "However, there was a recent genome-wide association study (GWAS) that identified SSPN as a candidate gene for atrial fibrillation (AF)." (PMID 37511627, 2023).
breast carcinoma (2 papers, 2022). "Four additional loci for MD or breast cancer risk, 5q23.2 (PRDM6), 8p21.2 (EBF2), 12p12.1 (SSPN), and 16q12.2 (FTO), were also found associated with V." (PMID 36344993, 2022). "Four additional V loci were identified from looking up MD and breast cancer susceptibility SNPs in GWAS of V, including 5q23.2 (PRDM6), 8p21.2 (EBF2), 12p12.1 (SSPN), and 16q12.2 (FTO)." (PMID 36344993, 2022). "FAM189A is down-regulated in breast cancer and SSPN is down-regulated in TNBC." (PMID 35906698, 2022).
limb-girdle muscular dystrophy (2 papers, 2017 to 2025). Limb-girdle muscular dystrophy (LGMD) is a heterogeneous group of muscular dystrophies characterized by proximal weakness affecting the pelvic and shoulder girdles. "Here, we advance these studies by revealing that SSPN provides scaffolding in δ-sarcoglycanopathies, enabling substitution of δ-sarcoglycan by its homolog, ζ-sarcoglycan, leading to the structural integrity of the DGC and prevention of limb-girdle muscular dystrophy R5." (PMID 40549548, 2025).
Obesity (2 papers, 2015 to 2024). Accumulation of substantial excess body fat. "NEW & NOTEWORTHY Young and aged sarcospan (SSPN)-deficient mice were examined to assess the role of SSPN in obesity and cardiometabolic disease." (PMID 39120469, 2024). "Overall, SSPN deficiency protected both sexes and ages from diet-induced obesity, with a greater effect in females." (PMID 39120469, 2024). "Numerous genes including sarcospan (SSPN) have been designated as obesity-susceptibility genes by human genome-wide association studies." (PMID 39120469, 2024). "With aging, SSPN deletion in males, however, offered less protection from diet-induced obesity, with a similar percent body weight change for WT and SSPN−/− mice, respectively." (PMID 39120469, 2024). "This suggests that SSPN deficiency alters additional parameters independent of diet-induced obesity." (PMID 39120469, 2024).
Arrhythmia (1 paper, 2023). Any cardiac rhythm other than the normal sinus rhythm. "Since SSPN has an important role in sarcolemma stabilization, variants in the gene may increase arrhythmia susceptibility by altering membrane stability and function/localization of membrane proteins involved with ion exchange and/or conduction." (PMID 37511627, 2023).
Becker muscular dystrophy (1 paper, 2024). Becker muscular dystrophy (BMD) is a neuromuscular disease characterized by progressive muscle wasting and weakness due to degeneration of skeletal, smooth and cardiac muscle. "Our human-specific monoclonal antibodies recognize endogenous SSPN in muscles from patients with Becker muscular dystrophy (BMD), where an abundance of this protein is significantly reduced compared to the levels of the SSPN protein at the sarcolemma of healthy muscles." (PMID 38892308, 2024).
cardiomyopathy (1 paper, 2024). A disease of the heart muscle or myocardium proper. "Rare PTVs in three prioritized genes, not established causes of cardiomyopathy, were found to be associated with binary diseases outcomes (MAP3K7 and NEDD4L with DCM) in at least one cohort and with quantitative traits (NEDD4L, MAP3K7 and SSPN) in UKB." (PMID 39572783, 2024).
congenital muscular dystrophy (1 paper, 2011). A muscular dystrophy that is characterized by diminished muscle tone (hypotonia), progressive muscle weakness and degeneration (atrophy), abnormally fixed joints, spinal rigidity, and delays in reaching motor milestones such as sitting or standing unassisted. "Noted that gene Q14714 (SSPN) in SG-SPN complex was associated with phenotype Fukuyama Congenital Muscular Dystrophy (FCMD) (MIM: 253800) which was closely related to phenotype (MIM: 608099) in our phenotype network, indicating that SG-SPN complex could indeed be a valid disease complex." (PMID 21799737, 2011).
glioma (1 paper, 2013). A benign or malignant brain and spinal cord tumor that arises from glial cells (astrocytes, oligodendrocytes, ependymal cells). "SSPN knockdown in a cultured glioma cell line (LN-229) did not affect cell division as determined by bromodeoxyuridine (BrdU) incorporation, but did increase vulnerability of glioma cells to hypoxia." (PMID 23282144, 2013).
Glucose intolerance (1 paper, 2024). Glucose intolerance (GI) can be defined as dysglycemia that comprises both prediabetes and diabetes. "In conclusion, SSPN deficiency in mice results in a lean phenotype under obesogenic conditions with accompanying glucose intolerance in both sexes of mice regardless of diet." (PMID 39120469, 2024).
lymphoma (1 paper, 2023). A malignant (clonal) proliferation of B- lymphocytes or T- lymphocytes which involves the lymph nodes, bone marrow and/or extranodal sites. "Meanwhile, CD52 and SSPN, as membrane proteins, probably directly participate in the interaction between lymphoma cells and tumor microenvironment and finally determine lymphoma dissemination." (PMID 37700827, 2023).
renal cell carcinoma (1 paper, 2024). "SSPN splicing is disrupted in many lung tumors, and the differential expression of SSPN has been reported in renal cell carcinoma." (PMID 38892308, 2024).
sarcoglycanopathies (1 paper, 2025). "SSPN-transgenic expression in the sarcoglycanopathy models (SgcaTG, SgcbTG, SgcgTG) revealed that disease pathology was mitigated in the Sgcg, but not Sgca or Sgcb." (PMID 40549548, 2025). "Given the capacity for SSPN to rewire cell-matrix interactions in the context of DMD, we tested whether SSPN overexpression in murine models of sarcoglycanopathy (Sgca, Sgcb, and Sgcg) would affect muscle cell adhesion in the LGMD disease context." (PMID 40549548, 2025).
tumor (3 papers, 2014 to 2023). "As KISS1R, KSR1, CAMK1, and SSPN have been either previously implicated in tumor cell migration or are known to participate in extracellular matrix adhesion, we wanted to explore whether any of these factors mediate RCC cell invasiveness." (PMID 24979721, 2014). "Of these, we further establish a role for CDH13 in tumor angiogenesis, as well as a pro-migratory role for four novel factors including KISS1R, KSR1, CAMK1, and SSPN in ccRCC." (PMID 24979721, 2014). "Immunohistochemistry (IHC) of ccRCC tumor tissue microarrays (TMA) for CAMK1 and SSPN demonstrated non-specific staining and could not be quantitatively analyzed." (PMID 24979721, 2014).
cancer (1 paper, 2014). A tumor composed of atypical neoplastic, often pleomorphic cells that invade other tissues. "SSPN expression has been studied in the context of muscle cell adhesion, strength, and regeneration; nonetheless, a role for SSPN in cancer has yet to be defined." (PMID 24979721, 2014). "Moreover, we implicate several of these gene hits not only in ccRCC for the first time (BHLHB3, CAMK1, CDH13, ENPP3, KCNJ2, KSR1, PLOD2, and TCF8), but also in a cancer model for the first time (CEP290, EFCAB3, PGBD5, RAPGEF5, SSPN, and TOX2)." (PMID 24979721, 2014).
SSPN also shares sentences with these, for which no sentence is quoted: brain disorder (1 paper); cardiovascular diseases (1); colon adenoma (1); coronary artery disease (1); myocardial infarction (1); sarcopenia (1).